CAT (catalase)
Diseases named in the same sentence as CAT in open-access papers (continued):
Sharing a sentence is not in itself a finding about the gene and the disease.
tumor (continued). "Membrane-associated catalase in cooperation with SOD protects the tumor cells (i) from intercellular HOCl signaling and (ii) from the aquaporin-mediated influx of NOX1/SOD-derived H2O2." (PMID 34679719, 2021). "In contrast, notably lower CAT mRNA levels (54/62 = 87.0%, p < 0.0001) were observed in tumor tissues than in associated normal tissues." (PMID 34676172, 2021). "Approach A was performed by abrogating the resistance of tumor cells towards exogenous H2O2 through application of neutralizing antibodies directed towards membrane-associated catalase, followed by addition of H2O2-generating glucose oxidase (GOX)." (PMID 34679719, 2021). "Tumor cells contribute to their death through further membrane-associated catalase inactivation and reactivation of intercellular apoptosis-inducing ROS and RNS signaling." (PMID 33920049, 2021). "It has been demonstrated that methylated CpG sites near the CAT promoter region are associated with catalase transcription and expression decline in liver tumor cell lines and tumor tissues." (PMID 32267380, 2020). "This study has determined membrane-associated catalase of tumor cells as the central target for primary and secondary 1O2 that is generated after the action of CAP and PAM." (PMID 31578342, 2019). "With membrane-associated catalase inactivated by 1O2, tumor cells would be expected to allow aquaporin-mediated influx of H2O2 into the cells." (PMID 31578342, 2019). "Gradually increasing concentrations of exogenous catalase caused gradually decreased apoptosis induction in the CAP-treated tumor cells." (PMID 31578342, 2019). "Sustained NOX1 activity and expression of membrane-associated catalase by tumor cells are the most remarkable redox-related differences between tumor cells and nonmalignant cells." (PMID 31578342, 2019). "In line with this conclusion, treatment of tumor cells with PAM caused the same degree of catalase inactivation as treatment with CAP, when CAP treatment was followed by an incubation step in the same medium." (PMID 31578342, 2019). "This triggers a massive, autoamplificatory generation of secondary 1O2 by the tumor cells, resulting in substantial inactivation of their membrane-associated catalase." (PMID 31578342, 2019). "The first step involves the formation of primary singlet oxygen (1O2) through the complex interaction between NO2− and H2O2.1O2 then inactivates some membrane-associated catalase molecules on at least a few tumor cells." (PMID 31578342, 2019). "As HOCl signaling was completely prevented in the presence of 8 U/ml exogenous catalase, the functional role of the targeted membrane-associated catalase of tumor cells for their protection was confirmed." (PMID 31578342, 2019). "CAP or PAM exposure only trigger this response by initially inactivating a small percentage of protective membrane associated catalase molecules on tumor cells." (PMID 31578342, 2019). "The interaction of these compounds was shown to result in the formation of primary 1O2 that caused local inactivation of membrane-associated catalase on tumor cells." (PMID 31558835, 2019). "Tumor cells are protected towards intercellular ROS/RNS signaling through tight control based on membrane-associated catalase that is supplemented by comodulatory SOD on the membrane of the cells." (PMID 31578342, 2019). "Inactivating tumor membrane-associated catalase is therefore a potentially attractive way to re-activate intercellular RONS-dependent apoptosis-inducing signaling." (PMID 31578342, 2019). "Conversely, tumor cells with relatively low catalase activity are expected to be more susceptible to ascorbate-mediated cell-death." (PMID 28107421, 2017). "Various studies have shown that the overexpression of membrane-associated catalase on the outer surface of tumor cells has a protective role against apoptosis induced intercellular ROS signaling." (PMID 26682014, 2016).
tumor (continued). "Several studies suggest an interesting mechanism protecting tumor cells against superoxide anion-mediated apoptosis by the expression of membrane-associated catalase." (PMID 27270647, 2016). "Nevertheless, the membrane-associated catalase can protect the tumor cell by preventing peroxynitrite generation and NO oxidation." (PMID 27270647, 2016). "As NOX1 expression and the expression of membrane-associated catalase has been found to be a regular feature of tumor cells, photofrin-derived singlet oxygen should induce the same sequence of biochemical steps in tumor cells other than MKN-45 as well." (PMID 26225731, 2015). "The selective action of extracellular singlet oxygen is based on its potential to target membrane-associated catalase of tumor cells." (PMID 26225731, 2015). "The combination of the two phenotypic features “NOX-dependent generation of extracellular superoxide anions” and “protection by membrane-associated catalase” has been found to be a regular trait in all human and rodent tumor cell lines tested." (PMID 26225731, 2015). "A Univariate Cox regression analysis showed that tumor size, venous invasion, tumor differentiation (Edmondson grade), tumor recurrence, and catalase expression were associated with overall survival (p<0.1)." (PMID 25361011, 2014). "Recently, decreased catalase activity was linked with increased tumor burden, while increased catalase activity corresponded with a decrease in tumor burden in male Skh-1 mice." (PMID 23691100, 2013). "Compared with PADI4 expression in the malignant tumors, cAT expression appeared to be more specific to malignant tumors and significantly associated with known tumor markers." (PMID 19183436, 2009). "An activation of UCP2 and UCP3 gene expression associated with an increase of catalase activity has previously been reported in atrophied gastrocnemius muscles of tumour-bearing rats." (PMID 19462004, 2009). "By analyzing levels of PADI4 and cAT, as well as the levels of known tumor markers, we aimed to explore the pathogenic role of PADI4 during carcinogenesis." (PMID 19183436, 2009). "The decline in antioxidant enzyme activity noted in cancer may be ascribed to various processes, including particular genetic variants of SOD and catalase, tumor-specific adaptations, and the effects of chemotherapy." (PMID 41596358, 2026). "Furthermore, CAT expression was positively associated with age (p-value 0.03), suggesting that aging contributes to cumulative oxidative damage in tumor tissues." (PMID 40149643, 2025). "Last, the surface interaction between NanoICD/CAT and ER leads to the activation of ICD-associated immune responses, while the integrated CAT efficiently alleviates tumor immunosuppression by decomposing H2O2 to O2, resulting in the activation and enhancement of anti-tumor immune responses." (PMID 38324678, 2024). "Increasing the endogenous NO concentration through methods like arginase inhibition, arginine addition, or NOD inhibition causes reversible catalase inhibition on tumor cell surfaces, leading to extracellular secondary singlet oxygen formation and FAS receptor activation." (PMID 38069213, 2023). "A loss of CAT activity during cancer development is associated with tumor formation and metastasis." (PMID 37176094, 2023). "GDY–CeO2 nanocomposites were formed by anchoring and dispersing cerium oxide nanoparticles on GDY; the composites showed superior catalase-mimicking activity, significantly alleviating tumor hypoxia, healing DNA damage caused by radiation, and inhibiting tumor growth." (PMID 36285317, 2022). "Therefore, efficient tumor progression requires the expression of membrane-associated catalase and superoxide dismutase (SOD), which interfere with ROS/RNS-mediated apoptosis-inducing signaling." (PMID 35646968, 2022).
tumor (continued). "Consequently, H2O2 and peroxynitrite that are produced continuously by tumour cells, and are usually decomposed by their protective membrane-associated catalase, are found to survive at the site of locally inactivated catalase." (PMID 33801451, 2021). "1O2 then inactivates some membrane-associated catalase molecules on at least a few tumour cells." (PMID 33801451, 2021). "However, catalase is relatively insufficient in tumor, causing the intratumoral excessive accumulation of H2O2." (PMID 34691545, 2020). "Among these, recently revealed selective anticancer effects of HNE generated by the non-malignant cells attenuating or even entirely blocking cancer-specific tumor membrane-associated catalase, might be of particular relevance." (PMID 32079077, 2020). "However, tumor cells express the membrane-associated catalase, which can efficiently decompose H2O2 directly after its generation." (PMID 27270647, 2016). "If these conclusions on autoamplification of singlet oxygen generation were correct, tumor cells that had been pretreated with exogenous singlet oxygen should cause inactivation of membrane-associated catalase in neighboring untreated cells through their own generation of singlet oxygen." (PMID 26225731, 2015). "Additionally, PADI4 and cAT levels were significantly associated with higher levels of known tumor markers." (PMID 19183436, 2009). "Moreover, it has been shown that elevated tumor CAT may be associated with CAT translocation from the peroxisome to the cell membrane, and thus its activity and protein levels may not reflect intracellular H2O2 clearance." (PMID 38790692, 2024). "Therefore, it may be concluded that mechanisms of tumor therapy that target membrane-associated catalase on NOX1-expressing tumor cells should require the cooperation of aquaporins with intercellular ROS/RNS-mediated signaling." (PMID 34679719, 2021). "Interestingly, it has been shown that high concentrations of HNE may inactivate membrane-associated catalase, leading to tumor cell death through mitochondria-derived apoptosis and consequently bestowing anti-cancer effects." (PMID 27270647, 2016). "The biochemical mechanisms described here might be considered as promising principle for the development of novel approaches in tumor therapy that specifically direct membrane-associated catalase of tumor cells and thus utilize tumor cell-specific apoptosis-inducing ROS signaling." (PMID 26225731, 2015). "Thus, NQO1:Catalase ratios in PDA tumor vs associated normal pancreas tissue potentially offer a significant therapeutic window that may be exploited using unique NQO1 bioactivatable drugs, such as ß-lap (ARQ761)." (PMID 26602448, 2015). "The novel radiosensitizer is intended for direct injection into the tumor, and only contains hydrogen peroxide and sodium hyaluronate, which are not generally associated with severe adverse effects as they are degraded into water and oxygen in the presence of peroxidase and catalase." (PMID 24959285, 2014). "This early event inactivates membrane-bound catalase, allowing tumor cell-derived H2O2 and peroxynitrite to initiate a self-amplifying cycle that produces secondary 1O2, as a hallmark of CAP selectivity." (PMID 41750590, 2026). "To investigate the ameliorative effects of ginsenoside Re on UVB-induced inflammation and oxidative stress in skin photodamage, we measured the levels of CAT, SOD, GSH-Px, MDA, T-AOC, IL-6, IL-8, and TNF-α in rat skin tissues." (PMID 41596360, 2026). "This study establishes dual thiol isomerase inhibition as a rational and effective strategy to simultaneously attenuate tumor growth and CAT." (PMID 41474368, 2026). "As a result, in the current study, the quantity of MDA, a byproduct of lipid peroxidation as well as reduced glutathione level, catalase and superoxide dismutase activities were assessed in tumor tissue." (PMID 41039030, 2025).
tumor (continued). "ZMRPC@HA exhibited catalase- and glutathione oxidase-like activities, primarily due to Ru3+, enabling the generation of oxygen and depletion of glutathione within the tumor, thereby synergistically improving PDT efficacy under hypoxic conditions." (PMID 41369447, 2025). "Parameters related to oxidative stress, including GSH, LPO, MDA, SOD, CAT, LA, PA, and hydroxyl radical scavenging activity, were measured using tumor samples." (PMID 40761482, 2025). "HMO also exhibits multiple enzyme‐mimicking activities, including peroxidase (POD), catalase (CAT), and glutathione peroxidase (GPx), amplifying oxidative stress through tumor‐specific catalytic reactions." (PMID 40056039, 2025). "Afterward, H2S gas was generated by (NH4)2S in an acidic tumor microenvironment, diffused into tumor cells, and then repressed intracellular catalase activity." (PMID 40926983, 2025). "When ECN accumulates within the hypoxic regions of tumors, it releases catalase, efficiently converting endogenous tumor H2O2 into O2." (PMID 41459231, 2025). "The catalase is expected to decompose the hydrogen peroxide, a reactive oxygen species inside tumours, into oxygen." (PMID 40650066, 2025). "Ultimately, HSA/CAT/LOX@IR808-mediated PDT led to marked tumor inhibition, prolonged survival, and reduced metastasis." (PMID 40704016, 2025). "For example, in one study, intratumoral hypoxia was reduced, and tumour radiosensitivity was increased by the use of a genetically modified form of the catalase-secreting, tumour-targeting probiotic EcN bacteria." (PMID 40792261, 2025). "GOx decomposes glucose in the tumor microenvironment into hydrogen peroxide, while CAT decomposes H2O2 inside and outside the tumor into oxygen, alleviating the hypoxic tumor microenvironment." (PMID 40358287, 2025). "The tumor-specific loss of catalase amplifies H2O2 production, leading to oxidative DNA lesions and selective tumor cell death." (PMID 40205952, 2025). "The loaded GOx selectively induces disulfidptosis in SLC7A11-overexpressing tumor cells, while CAT degrades H2O2 to alleviate hypoxia and inhibit oxidative stress, significantly reducing adhesion-related fibrosis." (PMID 40358287, 2025). "The nanocomplex CuCCT@CM-Ang—composed of polyethylene glycol, cisplatin, copper ions, tannic acid, and catalase—effectively penetrates the blood-brain barrier and selectively targets tumor sites, demonstrating high tumor tissue accumulation." (PMID 41267084, 2025). "Through a one-step method involving cysteine-reduced lysozyme-induced amyloid-like self-assembly, the film was co-loaded with GOx and CAT to achieve synergistic anti-adhesion and anti-tumor recurrence effects." (PMID 40358287, 2025). "While certain studies reveal that tumor cells can overexpress CAT to mitigate excessive hydrogen peroxide generated during rapid metabolic activity, thereby enhancing cancer cell survival." (PMID 40821783, 2025). "Researchers designed a multifunctional nanozyme with glutathione oxidase-, catalase-, and peroxidase-mimicking properties for catalytic treatment of tumor calls." (PMID 40666180, 2025). "FM was explored as an advanced sonosensitizer with CAT mimicking activity to alleviate tumor hypoxia to achieve excellent SDT performance under US irradiation." (PMID 39783849, 2025). "The synergistic effects of GOx and CAT in PTL@GC induce tumor cell disulfidptosis and alleviate hypoxia, while reducing oxidative stress and inflammation." (PMID 40358287, 2025). "The observed overexpression of SOD and CAT in tumor tissues reflects an upregulation of cellular mechanisms aimed at mitigating the high levels of ROS found in cancer." (PMID 40149643, 2025). "More importantly, the sonopiezoelectric therapeutic efficacy of HMO can be potentiated by their multiple enzyme‐mimicking activities of POD, GPx, and CAT under tumor microenvironment (TME)." (PMID 40056039, 2025).
tumor (continued). "Others regulate the energy metabolism, acidity, and redox balance of tumor cells, such as glucose oxidase (GOx), lactate oxidase (LOx), catalase (CAT), and tyrosinase (TYR)." (PMID 40565310, 2025). "Delivered to hypoxic tumor regions, these EMs enhance catalase stability and catalytic efficiency by virtue of their nanostructure, generating substantial O2 and significantly prolonging tumor oxygenation duration." (PMID 41459231, 2025). "In response to this challenge, novel nanoparticles are being developed to increase oxygen availability in the tumor microenvironment, for example, by using perfluorocarbonates as oxygen carriers or using catalase to convert hydrogen peroxide to oxygen." (PMID 40286175, 2025). "The ultra-pH-sensitive polymer enabled effective evasion of lysosomal degradation, ultimately ensuring efficient delivery of CAT to the tumor site." (PMID 40169560, 2025). "In the field of tumor treatment, catalase-based EMNMs exhibit their unique merits in tumor inhibition and tissue penetration." (PMID 39896991, 2025). "This synergistic mechanism will enable the protein film loaded with glucose oxidase (GOx) and catalase (CAT) (PTL@GC) to exhibit significant advantages in inhibiting tumor recurrence and preventing adhesion." (PMID 40358287, 2025). "To further confirm the link between apoptosis and oxidative stress, we employed an ELISA to measure SOD and CAT activity in the sera of tumor‐bearing mice." (PMID 41394539, 2025). "In fact, Zińczuk et al26 have demonstrated that the SOD level is obviously higher in tumor tissues than in normal colonic mucosa tissues, while CAT activity depended on the intensity of inflammatory infiltration." (PMID 39873359, 2025). "Mn/SAE catalyzed the H2O2 conversion to O2 molecules based on its catalase activity in 4T1 tumor-bearing BALB/c mice." (PMID 40666180, 2025). "The catalase expressed in engineered M1 macrophage‐derived EVs resulted in the alleviation of tumor hypoxia, and the DDRi loaded in engineered EVs led to the suppression of DNA damage repair." (PMID 40600457, 2025). "The delivery of exogenous CAT to alleviate tumor hypoxia can be accomplished using different nanoagents." (PMID 40051791, 2025). "For CAT-triggered hypoxia modulation, efficient encapsulation of CAT, accurate delivery of CAT to tumor sites, and generation of oxygen remain the major challenges." (PMID 40051791, 2025). "Building on the strategy of leveraging CAT activity to mitigate tumor hypoxia, researchers have also explored the use of inorganic nanozymes that mimic CATfunction." (PMID 41294574, 2025). "This leads to an increase in SOD levels and, more importantly, an increase in catalase levels, which protects tumor cells." (PMID 40227274, 2025). "The PMOF@AuNP/hairpin nanotheranostic showed catalase activity to catalyze H2O2 to O2 to ameliorate tumor hypoxia and thus enhance the PDT effect." (PMID 40375976, 2025). "The heat generated by the photothermal effects additionally accelerates catalase to produce O2, reducing hypoxia in the tumor microenvironment." (PMID 39830015, 2025). "These nanoparticles break down in the acidic tumor environment and rapidly release catalase to generate oxygen in situ from endogenous H2O2, significantly increasing PDT efficacy in hypoxic tumors." (PMID 41471095, 2025). "By reducing hypoxic circumstances and catalyzing endogenous H2O2, the integrated catalase enzyme can produce O2 at the tumor site and lessen tumor resistance." (PMID 41245513, 2025). "A considerable inhibition in catalase by 34% and further significant attenuation of 56% were observed in tumor tissue of Myricetin and Myr-NE-treated xenografts, respectively, compared to control." (PMID 40552278, 2025). "The expression levels of p-GSK-3β and p-p70S6K in tumor tissues with overexpression of catalase or GPX were greatly decreased." (PMID 39660100, 2025).